VIM (vimentin)
Diseases named in the same sentence as VIM in open-access papers (continued):
Sharing a sentence is not in itself a finding about the gene and the disease.
phyllodes tumor (2 papers, 2014 to 2025). A benign, borderline, or malignant fibroepithelial neoplasm arising from the breast and rarely the prostate gland. "Moreover, vimentin’s role in epithelial–mesenchymal transition suggests that its expression may be linked to the invasive potential of phyllodes tumors." (PMID 41155869, 2025). "The assessment of vimentin can aid in distinguishing phyllodes tumors from other breast lesions, particularly in cases where the histological features are ambiguous." (PMID 41155869, 2025). "In phyllodes tumors, vimentin expression is typically strong, reflecting the stromal component of these neoplasms." (PMID 41155869, 2025).
primary biliary cirrhosis (2 papers, 2016 to 2021). "Neoexpression of S100A4, vimentin, Snail, and MMP-2, associated with downregulation of E-cadherin and K19 in the bile ducts, were observed in histological samples of patients with primary biliary cirrhosis (PBC), primary sclerosing cholangitis, and biliary atresia (BA)." (PMID 26880950, 2016).
pulmonary tuberculosis (2 papers, 2017 to 2024). A bacterial infection that affects the lungs and is caused by Mycobacterium tuberculosis. "When analyzing autoantibodies in patients with pulmonary tuberculosis, we found a high level of antibodies to modified citrullinated vimentin (anti-MCV compared to other antibodies." (PMID 39765749, 2024). "This response was not seen with vimentin stimulation of PBMCs from healthy volunteers or those with pulmonary tuberculosis." (PMID 28114394, 2017).
salivary gland cancer (2 papers, 2021 to 2025). A primary or metastatic malignant neoplasm that affects the major or minor salivary glands. "Immunohistochemical staining can assist in the diagnosis because RCC metastases show a strong reaction to vimentin, as well as focal cytokeratin (CK) positivity; by contrast, minor salivary gland cancers show diffuse CK positivity." (PMID 33809250, 2021).
signet ring cell carcinoma (2 papers, 2012 to 2021). A usually aggressive, poorly differentiated invasive adenocarcinoma characterized by the presence of malignant glandular cells in which the nucleus is pressed to one side by the presence of intracytoplasmic mucus. "Vimentin is aberrantly expressed in only one case of signet-ring cell carcinoma, which is poorly differentiated with nodal and distant metastases (p = 0.001)." (PMID 34214117, 2021). "Moreover, vimentin is aberrantly expressed in one case of signet-ring cell carcinoma." (PMID 34214117, 2021). "In our case, negativity to Vimentin and positivity to CEA proved useful in excluding primary signet-ring cell carcinoma of the endometrium an entity even rarer than PCSRCC." (PMID 22236794, 2012).
small cell carcinoma (2 papers, 2014 to 2025). A neuroendocrine carcinoma composed of small malignant cells which are often said to resemble "oat cells" under the microscope. "Hence, a wider range of immunohistochemical markers, including chromogranin and TTF-1 to support a diagnosis of small cell carcinoma, and CD99, vimentin, or FLI1 for PNET should be used for the differential diagnosis." (PMID 25475214, 2014).
smooth muscle neoplasm (2 papers, 2012 to 2015). "Immunohistochemical study revealed neoplastic cells negative for cytokeratin, and positive for vimentin and α-smooth muscle actin, which his consistent with an IHC profile of a smooth muscle neoplasm." (PMID 22747606, 2012).
soft tissue tumors (2 papers, 2021 to 2024). "Vimentin—a marker for soft tissue tumors, but also expressed in various epithelial cancers—was examined immunohistochemically in only five presacral NETs, but it was detected in four of five cases." (PMID 34690926, 2021). "Immunohistochemical analysis of primary desmoplastic fibroblastoma of the bone showed expression similar to that of soft tissue tumors, including consistent diffuse positivity for vimentin and focal to absent reaction for smooth muscle markers, such as SMA." (PMID 39830562, 2024).
spindle-cell malignant melanoma (2 papers, 2021 to 2026). "Histopathological examination showed spindle-cell malignant melanoma with diffuse Melan-A and vimentin expression and focal S100 positivity, while epithelial markers were negative." (PMID 41694883, 2026). "Differences in the expression of vimentin and actin in spitz nevi and spitzoid malignant melanoma were detected by mass spectrometry in a previous study, but the results could not be validated by immunohistochemistry." (PMID 34206844, 2021).
systemic sclerosis (2 papers, 2022 to 2025). A chronic disorder, possibly autoimmune, marked by excessive production of collagen which results in hardening and thickening of body tissues. "Notably, serum citrullinated vimentin (VICM) levels serve as a biomarker of disease activity in systemic sclerosis, showing significantly elevated concentrations in patients with rapid disease progression compared to healthy controls." (PMID 41280911, 2025). "Thus, the vimentin immunization model may provide a valuable tool for developing new therapeutic strategies for systemic sclerosis." (PMID 41280911, 2025).
temporal lobe epilepsy (2 papers, 2023 to 2025). A localization-related (focal) form of epilepsy characterized by recurrent seizures that arise from foci within the temporal lobe, most commonly from its mesial aspect. "In drug-resistant temporal lobe epilepsy associated with FCD, adults exhibit higher GFAP/S100/caspase-3, while children show more vimentin, with region-dependent patterns." (PMID 41155206, 2025).
teratocarcinoma (2 papers, 2019 to 2022). A germ cell tumor characterized by the presence of an embryonal carcinoma component and a teratoma component. "No tumors developed in the non-inflammatory AOM cancer model in Vim−/− mice, which is consistent with the earlier report that the absence of vimentin has no discernible effect on tumorigenesis in a teratocarcinoma model." (PMID 35399505, 2022).
testicular tumours (2 papers, 2011 to 2023). "Due to the good differentiation of both testicular tumours, immunohistochemistry was only performed for vimentin, CK and Melan A. Histological appearance of most testicular tumours in dogs is highly specific and immunophenotyping of the neoplasia is not necessary." (PMID 21255434, 2011).
thrombosis (2 papers, 2014 to 2015). "By employing a different methodological approach for detection of aPL, such as TLC immunostaining, as well as new antigenic targets of APS, such as vimentin/cardiolipin complex, it may be possible to detect aPL/cofactors in about two-thirds of SN-APS patients with thrombosis or pregnancy morbidity." (PMID 25874238, 2015).
tongue tumors (2 papers, 2019 to 2022). "We found vimentin, the mesenchymal protein, to be the most upregulated protein in tongue tumor tissues compared to adjacent apparent normal tissues." (PMID 35498535, 2022). "There was decreased vimentin positivity identified in tongue tumors that was ulcerated 10% (2/20) compared to the exophytic and infiltrating (p = 0.014; χ2 = 8.536)." (PMID 35498535, 2022).
undifferentiated pleomorphic sarcoma (2 papers, 2017 to 2024). An undifferentiated soft tissue sarcoma characterized by the presence of a pleomorphic malignant cellular infiltrate. "The tumor cells, which were only positive for vimentin, supported the diagnosis of undifferentiated pleomorphic sarcoma (UPS)." (PMID 39449379, 2024). "After the wide resection of tumor in the left thigh, the patient was diagnosed as undifferentiated pleomorphic sarcoma (UPS) with positive CD 68 and Vimentin expression." (PMID 27888623, 2017).
Uterine leiomyoma (2 papers, 2010 to 2022). The presence of a leiomyoma of the uterus. "The human uterine leiomyoma (UtLM) cells were positive for both desmin (center) and vimentin (upper left)." (PMID 20537183, 2010). "Furthermore, miR-29 inhibitors promoted the protein expression of MMP-2 and MMP-9 (P < 0.01), and EMT promoting proteins N-cadherin, snail, vimentin, and Transwell assay showed that miR-29 inhibitors promoted cell migration in uterine leiomyoma (P < 0.01)." (PMID 35113040, 2022).
uveitis (2 papers, 2010 to 2011). An inflammatory process affecting a part of or the entire uvea. "In order to further characterize the expression patterns of fibronectin and osteopontin within the equine retina, we performed triple labellings of healthy and uveitis diseased retina sections with the Müller cell marker vimentin." (PMID 22194789, 2011). "The presence of antibodies recognizing α-crystallin B, vimentin and β-crystallin B2 in uveitic, but not normal eye fluids, strongly suggests a role for these antibodies in Leptospira-associated recurrent uveitis." (PMID 20689825, 2010). "The biological significance of α-crystallin B, vimentin and β-crystallin B2 as a cross-reacting antigen was investigated by examining antibody levels against these lenticular or retinal proteins in eye fluids obtained from clinical cases of leptospiral uveitis and healthy controls." (PMID 20689825, 2010).
vulvar carcinoma (2 papers, 2022 to 2026). "Our laboratory found that the epithelial vulvar cancer cell line A431 undergoes permanent loss of E-cadherin and gains vimentin expression when treated with a corticosteroid known as clobetasol (referred to as A431D cells)." (PMID 41658172, 2026).
Zinc deficiency (2 papers, 2015 to 2025). A deficiency of the essential metal Zinc; an essential cofactor for many enzymes. "Our results show that either acute or chronic zinc deficiency disturbs vimentin function and susceptibility to stress, potentially contributing to pathophysiology." (PMID 26031447, 2015). "Therefore, the potential involvement of impaired vimentin function in the alterations associated with zinc deficiency deserves further investigation." (PMID 26031447, 2015). "The levels of CDH2, Vimentin, and SNAIL were significantly downregulated compared with the zinc deficiency group, while CDH1 expression was restored." (PMID 39028478, 2025). "Specifically, our findings demonstrate that zinc deficiency significantly upregulates the expression of CDH2, Vimentin, and Snail in renal tissues while downregulating CDH1." (PMID 39028478, 2025). "In this study, we conducted a comprehensive assessment of the expression patterns of key EMT markers (N-cadherin, E-cadherin, Vimentin, SNAIL) and fibrosis-related markers (α-SMA, FN1, Col III) in a rat model with zinc deficiency using qPCR, WB analysis, and IHC." (PMID 39028478, 2025).
abortion (1 paper, 2025). the ending of pregnancy by removing a fetus or embryo before it can survive outside the uterus. "Importantly, anti-CXCL9 treatment effectively reversed the expression of E-cadherin and Vimentin in the placentas of LPS-induced abortion mice." (PMID 41280905, 2025).
acinic cell carcinoma (1 paper, 2018). "On the other hand, although specific molecular alterations that characterize acinic cell carcinoma have not yet been elucidated, activations of β-catenin and vimentin were reported in previous studies." (PMID 30652068, 2018).
acne (1 paper, 2014). An inflammatory process of the sebaceous glands which is characterized by comedones, nodules, papules and/or pustules on the skin. "The possibility exists that keratinocytes are under stress in acne-affected follicles leading to morphological alterations going along with vimentin expression." (PMID 25238151, 2014). "Taken together, it is tempting to speculate that the presence of vimentin in SFIs extracted from acne-affected skin is exploited by P. acnes, i.e. vimentin-positive cells might be invaded by P. acnes." (PMID 25238151, 2014). "Whereas the presence of inflammation-associated human proteins in SFIs from acne-affected skin was expected, and is in agreement with previous studies, the presence of vimentin in most acne but not in healthy samples was surprising." (PMID 25238151, 2014).
acrodermatitis enteropathica (1 paper, 2020). Acrodermatitis enteropathica (AE) is a rare inherited inborn error of metabolism resulting in a severe zinc deficiency and characterized by acral dermatitis, alopecia, diarrhea and growth failure. "We have previously observed that zinc-deficient fibroblasts from a patient with a genetic alteration of zinc transport (acrodermatitis enteropathica) displayed vimentin filaments/bundles narrower than those of cells from a control subject, a condition that could be improved by zinc supplementation." (PMID 32244501, 2020).
actinic keratosis (1 paper, 2022). A precancerous lesion of the skin composed of atypical keratinocytes. "We examined the effect of MDK on fibroblasts by investigating the expression of MDK and VIM (a general marker of fibroblasts) in normal skin and actinic keratosis (AK) samples." (PMID 36438481, 2022).
acute T cell leukemia (1 paper, 2023). "In Jurkat cells, which are commonly used in studies of acute T cell leukemia, T cell signaling, as well as used as an expression system for various chemokine receptors, we transiently transfected suspension cells and successfully tagged five out of six targeted proteins except for VIM." (PMID 37487103, 2023).
adenosarcoma (1 paper, 2020). A low grade malignant neoplasm characterized by the presence of a benign epithelial component (tubular and cleft-like glands) and a low grade sarcomatous component that contains varying amounts of fibrous and smooth muscle tissues. "The most common immunohistochemical markers for the sarcomatous component of adenosarcomas are CD10 (71–100%), WT1 (79%), and vimentin (86%)." (PMID 32972432, 2020).
adenovirus infection (1 paper, 2015). "Expression of E-cadherin was increased in HIBECs following Trps1 adenovirus infection and CP/reperfusion injury (CPRI), with vimentin expression levels reduced and CPRI-mediated epithelial-mesenchymal transition (EMT) inhibited." (PMID 25886207, 2015).
adrenal neuroblastoma (1 paper, 2019). "Microscopic and immunohistochemical staining, which were positive for synaptophysin, CD56, and vimentin, confirmed the diagnosis of adrenal neuroblastoma." (PMID 31500669, 2019).
airway hyperresponsiveness (1 paper, 2022). "PLK1, a serine/threonine-protein kinase, contributes to reducing airway resistance and airway hyperresponsiveness in asthmatic mice by regulating vimentin phosphorylation at Ser-56." (PMID 36393974, 2022).
allergic asthma (1 paper, 2022). A asthma with a basis in a pathological type I hypersensitivity reaction. "In a mouse model of allergic asthma, acute HDM exposure significantly increased TGFβ1 protein in the BAL fluid, decreased expression of CDH1 and occludin in the airway epithelium, and increased expression of VIM, αSMA and pro-collagen 1 in the mesenchyme." (PMID 36230980, 2022).
Alpha-thalassemia (1 paper, 2022). Alpha-thalassemia is an inherited hemoglobinopathy characterized by impaired synthesis of alpha-globin chains leading to a variable clinical picture depending on the number of affected alleles. "In addition to histone H3K27M mutation, immunohistochemical staining showed that the tumor cells were positive for glial fibrillary acidic protein, oligodendrocyte transcription factor 2, alpha-thalassemia/mental retardation syndrome X, S-100 and Vimentin." (PMID 35713454, 2022). "Immunohistochemical staining revealed that the tumor cells were positive for GFAP, oligodendrocyte transcription factor 2, histone H3K27M mutant protein, alpha-thalassemia/mental retardation syndrome X, S-100 and Vimentin, but negative for IDH1 R132H, Syn and NeuN." (PMID 35713454, 2022).
American trypanosomiasis (1 paper, 2018). "We search for anti-vimentin antibodies in human sera from controls or Americantrypanosomiasis patients." (PMID 29538505, 2018). "In this work we studiedvimentin distribution on LLC-MK2 cells infected with T.cruzi andanti-vimentin antibodies in sera from several clinical pictures of AmericanTrypanosomiasis, in order to elucidate any vimentin involvement in the humoralresponse of this pathology." (PMID 29538505, 2018).
anaplastic cancer (1 paper, 2022). "Vimentin was found to have a sensitivity of 95% and a specificity of 91% in anaplastic cancers." (PMID 35154933, 2022).
anaplastic large cell lymphoma (1 paper, 2021). Anaplastic large cell lymphoma (ALCL) is a rare and aggressive peripheral T-cell non-Hodgkin lymphoma, belonging to the group of CD30-positive lymphoproliferative disorders, which affects lymph nodes and extranodal sites. "Spindle cell carcinoma of the skin co-expresses cytokeratin and vimentin, and anaplastic large cell lymphoma may express cytokeratins." (PMID 34203756, 2021).
anemia (1 paper, 2012). A reduction in the number of red blood cells, the amount of hemoglobin, and/or the volume of packed red blood cells. "We describe herein, a 51-year-old Asian female initially manifested with signs of severe anemia who presented with a lung mass unrelated to pleura that was morphologically typical EMC, with strong immunoreactivity for vimentin and NSE." (PMID 22925697, 2012).
Anorexia (1 paper, 2016). Lack of desire to eat (loss of appetite). "Accordingly, GFAP+ cells deficit may be replaced by vimentin+/nestin+ cells in anorexia." (PMID 27579183, 2016). "Additionally, anorexia increased the expression of the intermediate filaments vimentin and nestin." (PMID 27579183, 2016). "We conclude that anorexia reduces the hippocampal GFAP+ cell density and increases vimentin and nestin expression." (PMID 27579183, 2016).
antiphospholipid syndrome (1 paper, 2015). A disorder caused by the presence of autoantibodies directed against phospholipids, causing a hypercoaguable state, which may result in blood clots, stroke, heart attack, and in women, significant pregnancy-related complications, including miscarriage and still birth. "The association of CL with vimentin at the cell surface may represent a “new” target antigen in the context of the apoptotic origin of anti-vimentin/CL autoantibodies in Antiphospholipid Syndrome." (PMID 26491702, 2015).
appendicitis (1 paper, 2019). Acute inflammation of the vermiform appendix. "Pathology identified appendicitis and serosal involvement of GIST in all specimens staining positive for CD68, CD117, and vimentin." (PMID 30918739, 2019).
Arthralgia (1 paper, 2020). "The remaining three arthralgia patients had one of the three citrullinated specificities; two displayed vimentin-reactive and one CILP/fibrinogen-specific T cells." (PMID 32423478, 2020). "One of the five arthralgia patients displayed reactivity against all citrullinated peptides, while another one had vimentin- and α-enolase-specific T cells." (PMID 32423478, 2020).
atrial fibrillation (1 paper, 2023). A disorder characterized by an electrocardiographic finding of a supraventricular arrhythmia characterized by the replacement of consistent P waves by rapid oscillations or fibrillatory waves that vary in size, shape and timing and are accompanied by an irregular ventricular response. "Another group found that heart tissue from patients undergoing ablation for atrial fibrillation (AF) exhibited increases in senescence markers co-localized with vimentin and α-SMA." (PMID 37174697, 2023).
autoimmune uveitis (1 paper, 2011). An autoimmune form of uveitis (disease). "In uveitic retina sections, a characteristic vimentin upregulation indicates Müller cell gliosis as it occurs in autoimmune uveitis." (PMID 22194789, 2011).
B-cell lymphomas (1 paper, 2018). "However, the predominance of N-terminal vimentin immunoreactivity in B-cell lymphomas, and the frequent presence of N-terminal reactivity in healthy subjects in the current study, suggest that N-terminal immunoreactivity is a common phenomenon in the healthy B-cell repertoire." (PMID 30038611, 2018).
bacteremia (1 paper, 2016). "In the neonatal murine model of E. coli meningitis, vimentin -/- and IbeA deletion in E. coli K1 (ZD1) did not change the bacteremia level." (PMID 27657497, 2016).